STEEP1 (STING1 ER exit protein 1)
Description:
Molecular adapter that stimulates membrane curvature formation and subsequent endoplasmic reticulum exit site (ERES) establishment by recruiting PI3K complex I, leading to COPII vesicle-mediated transport. Promotes endoplasmic reticulum (ER) exit of cGAMP-activated STING1 oligomers.
Synonyms: STEEP; CXorf56; FLJ22965; MRX107; XLID107
Tractability: Small molecule: a structure with a bound ligand is known. Antibody: UniProt places it where antibodies can reach, with high confidence. PROTAC: ubiquitination databases record sites on it.
Gene: Protein-coding gene on chromosome X (119,535,669 to 119,565,409, reverse strand). Ensembl gene ENSG00000018610.
Subcellular location: Cytoplasm; Endoplasmic reticulum membrane; Nucleus
Subcellular location (Human Protein Atlas): Nucleoplasm; Centrosome
Pathways (Reactome):
Metabolism of RNA: mRNA Splicing - Major Pathway
Gene Ontology:
Molecular function: protein binding; protein-macromolecule adaptor activity
Biological process: endoplasmic reticulum membrane organization; endoplasmic reticulum to Golgi vesicle-mediated transport
Cellular component: cytoplasm; endoplasmic reticulum; endoplasmic reticulum membrane; nucleoplasm; nucleus; cell body
Gene-disease validity (ClinGen):
ClinGen rates the evidence that STEEP1 causes each of these diseases.
intellectual disability, X-linked 107 (X-linked): Moderate.
Homologues: Orthologues: dog STEEP1 (100% identical), guinea pig STEEP1 (100% identical), pig STEEP1 (100% identical), mouse Steep1 (99% identical), chimpanzee STEEP1 (95% identical), tropical clawed frog steep1 (91% identical), rat Steep1 (91% identical), zebrafish steep1 (89% identical), rabbit STEEP1 (77% identical), Drosophila melanogaster CG16865 (51% identical), Caenorhabditis elegans Y66D12A.8 (40% identical).
Diseases named in the same sentence as STEEP1 in open-access papers:
STEEP1 is named in the same sentence as 14 diseases in open-access papers, as found by Europe PMC text mining. Sharing a sentence is not in itself a finding about the gene and the disease. The quoted sentences say what the papers report.
X-linked intellectual disability (1 paper, 2023). An X-linked intellectual deficiency in which not enough information is known, reported or published to indicate whether a gene causes non-syndromic or syndromic presentations. "Mutations in STEEP1 cause X-linked intellectual disability and other neurological disorders." (PMID 37085889, 2023).
STEEP1 also shares sentences with these, for which no sentence is quoted: Intellectual disability (3 papers); cancer (2); neurological disorder (2); breast carcinoma (1); hypospadias (1); neurodevelopmental disorder (1); Obesity (1); oral carcinoma (1); overgrowth syndrome (1); thymoma (1); triple-negative breast carcinoma (1); tumor (1); X-linked Nascimento-type intellectual disability syndrome (1).